POSTN (periostin)
Diseases named in the same sentence as POSTN in open-access papers (continued):
Sharing a sentence is not in itself a finding about the gene and the disease.
melanoma (continued). "Since our FNA technology failed to capture CAFs, we investigated POSTN and MDK expression in the tumor microenvironment of targeted therapy-resistant melanoma biopsies using the Tumor Profiler dataset." (PMID 38942020, 2024). "Second, periostin has been observed in the peripheral cytoplasm of human bladder cancer cell line SBT991, as opposed to the homogeneous cytoplasm expression in mouse melanoma cell line B16F10." (PMID 26981774, 2016). "To prove our hypothesis, we performed immunohistochemical staining for POSTN and CD163 in five patients with in-transit advanced melanoma without irAEs, and in two patients with in-transit advanced melanoma with irAEs." (PMID 29643991, 2018).
eosinophilia (38 papers, 2012 to 2026). "Stronger expression of periostin is associated with remodeling changes and tissue eosinophilia > 10/HPF." (PMID 37046572, 2023). "Serum periostin is linked to type 2 biomarkers, including eosinophilia, IgE concentration, and the fraction of NO (FeNO) inhalation, IL-4, and TSLP." (PMID 36611844, 2022). "The plasma concentration of periostin, a matricellular protein commonly associated with eosinophilia significantly decreased in the hMMP-2 TG/OVA group compared to the WT/OVA group." (PMID 31428095, 2019). "Correspondingly, the intranasal inhalation of allergens from A. fumigatus in a recent study of periostin-deficient mice demonstrated that fewer eosinophils were recruited to the lung, concomitant with an increase in blood eosinophilia." (PMID 25981515, 2015). "Interestingly, certain sputum biomarkers associated with sputum eosinophilia, such as periostin, can identify SA patients with PAO." (PMID 41302936, 2025). "Conventional systemic biomarkers, including blood eosinophilia, serum periostin, and serum sIgE, have been proven to be predictive markers for the response to omalizumab in landmark studies." (PMID 40313547, 2025). "Blood eosinophilia was positively correlated with the serum concentrations of periostin (r = 0.35, p < 0.05), IL-6 (r = 0.49, p < 0.05), IL-10 (r = 0.66, p < 0.05), IL-12p70 (r = 0.39, p < 0.05), and ADAM33 (r = 0.59, p < 0.05)." (PMID 36835202, 2023). "Higher periostin levels were related to increased basement membrane thickness, subepithelial fibrosis, and eosinophilia among patients undergoing surgery for CRS." (PMID 36611844, 2022). "For example, BAL periostin occurred to be a strong predictor of thicker RBM, whereas BAL eosinophilia was associated with higher collagen I accumulation." (PMID 34204767, 2021). "By contrast, only 15% of COPD patients and 0% in the control group had elevated sputum eosinophilia with high periostin and TSLP levels at the same time." (PMID 33203095, 2020). "Association of sputum periostin levels with upper airway indices (olfactory function, CRS symptoms, resected sinus and NP tissue eosinophilia, and radiological CRS severity) were also analysed, along with sputum cells and FeNO levels." (PMID 32015784, 2020). "A significant positive correlation of IS periostin at both protein and mRNA levels with sputum eosinophilia in asthmatics is in line with the earlier observations." (PMID 33203095, 2020). "The most common endotype is one described as “type-2-high” (i.e. high levels of interleukin [IL]-13, eosinophilia, and periostin)." (PMID 28721208, 2017). "Although airway eosinophilia and high periostin levels were common to clusters E and F, cluster F had the additional component of neutrophilic inflammation, leading to higher symptom scores and a mixed granulocytic subtype." (PMID 26851968, 2016). "This study evidenced the superiority of serum periostin for predicting sputum and tissue eosinophilia, compared to blood eosinophils, IgE levels, YKL-40 and FeNO." (PMID 26430389, 2015). "In our study, we found that periostin levels were strongly correlated with peripheral eosinophilia levels and could be helpful in differentiating eosinophilia despite systemic steroid use." (PMID 36326393, 2022). "In addition, serum periostin levels were increased in the presence of eosinophilia independent from atopy and it can help to differentiate eosinophilia even if the patient is under systemic steroid therapy." (PMID 36326393, 2022). "Measurement of serum periostin has been shown to be superior at identifying airway eosinophilia (defined as a composite of bronchial biopsy or sputum eosinophilia) than sputum alone or FeNO alone, although this was not seen in another study when looking at sputum eosinophilia alone." (PMID 29301585, 2018).
eosinophilia (continued). "Our study showed that serum periostin levels were decreased in viral infection-induced exacerbations and increased in the presence of eosinophilia independent from atopy and it can help to differentiate eosinophilia even if the patient is under long-term systemic steroid therapy." (PMID 36326393, 2022). "Periostin is associated with a type 2 pattern of inflammation, the sensitivity and specificity of the assay used in this study for the prediction of airway eosinophilia has not yet been determined." (PMID 30001712, 2018). "The results of the biomarker analysis showed that periostin, PAPP-A, CST-2, SerpinF2 and eosinophilia showed similar courses to NPS." (PMID 36969262, 2023). "Biomarker trends (e.g., decreased IgE, periostin) further guide therapeutic decisions, though transient eosinophilia post-dupilumab does not indicate failure." (PMID 41602869, 2026). "We found that two-thirds of mild-to-moderate atopic asthma patients who were not treated with ICC had IS eosinophilia together with relatively high IS periostin and TSLP levels." (PMID 33203095, 2020). "We have also demonstrated a significant correlation between eosinophilia of NPs and sputum periostin and FeNO levels, but not sputum eosinophils." (PMID 32015784, 2020). "Periostin did not correlate with eosinophilia, blood IgE, or other basic laboratory tests." (PMID 28429138, 2017). "Periostin, gender, BMI, NLR, PLR, SII, and eosinophilia were not significant predictors in the multivariable model (all p > 0.05)." (PMID 41374409, 2025). "IL-4, IL-5, IL-13, ALOX15, CST1, POSTN, and CCL26 were significantly elevated in patients who had eosinophilia higher than 5%, but not IFN-γ." (PMID 40978168, 2025). "The results revealed that unlike IFN-γ, IL-4, IL-5, IL-13, ALOX15, CST1, POSTN, and CCL26 were significantly elevated in patients with eosinophilia greater than 5%." (PMID 40978168, 2025). "However, the mechanism by which eosinophils are selectively recruited in nasal polyps remains to be clarified, and whether periostin might influence the tissue eosinophilia of ENP by modulating eotaxin-2 and RANTES secretion is not clear and warrants further investigation." (PMID 37046572, 2023).
gastric cancer (38 papers, 2012 to 2025). A primary or metastatic malignant neoplasm involving the stomach. "Previous studies indicate that fibroblasts with high CTHRC1 and POSTN expression are markers for gastric cancer-associated fibroblasts." (PMID 39850884, 2024). "Periostin, an extracellular matrix protein that functions in tooth and bone remodeling, is produced by cancer-associated fibroblasts and supports growth of gastric cancer through the activation of ERK." (PMID 26176534, 2015). "Periostin expression was significantly associated with poor prognosis in gastric cancer patients." (PMID 36230803, 2022). "Interestingly, in patients with intestinal type gastric cancer, low periostin levels were associated with poor survival and lymph node metastasis." (PMID 33466303, 2021). "Here, we used LC-MS/MS, SPR, and co-immunoprecipitation to demonstrate that periostin is a NINJ2 binding partner in gastric cancer cells." (PMID 40518514, 2025). "A recent study suggests that periostin secreted by podoplanin positive-CAFs induces metastasis and stemness in gastric cancer cells through PI3K/AKT and FAK/YAP activation, respectively." (PMID 38562556, 2024). "This study confirmed that decreased periostin levels attenuate gastric cancer cells’ stemness properties, such as sphere formation." (PMID 38562556, 2024). "Single-cell sequencing of gastric cancer tissues revealed that POSTN-expressing CAFs promote gastric cancer invasion and metastasis by degrading the ECM and attracting tumor-associated M2-like macrophages to form a niche conducive to metastasis." (PMID 37143134, 2023). "All second-generation gastric cancer sample-derived cells expressed COL1A1, and approximately 18% of cells expressed periostin, indicating that we obtained gastric cancer CAFs and that some CAFs were eCAFs." (PMID 34976204, 2022). "Periostin also enhances the growth of gastric cancer-cell lines accompanied by the activation of extracellular signal-regulated kinase (ERK)." (PMID 30131847, 2018). "Periostin is overexpressed in gastric cancer cells that are resistance to cisplatin and 5-fluorouracil (5-FU)." (PMID 28754000, 2017). "POSTN was also expressed in CAF in gastric cancer and enhanced the proliferation of gastric cancer cell lines by activation of ERK26." (PMID 26892343, 2016). "The importance of stromal POSTN was also demonstrated in another study in which orthotopic inoculation of gastric cancer cells into Rag2−/−; Postn−/− mice reduced tumor size, decreased invasiveness, and decreased growth compared to Rag2−/−; Postn+/+ mice." (PMID 26086719, 2015). "Furthermore, periostin levels are elevated in primary gastric cancer and metastatic lymph nodes when compared to benign gastric conditions." (PMID 40518514, 2025). "POSTN has also been reported to be expressed on CAFs in colorectal and gastric cancer." (PMID 39195230, 2024). "Likewise, overexpression of POSTN in a human gastric carcinoma cell line resulted in decreased 5-fluorouracil-induced apoptosis." (PMID 38942020, 2024). "The same study revealed that high periostin levels in diffuse gastric cancer was associated with high M2 macrophage infiltration, whereas this was not the case in intestinal gastric cancer." (PMID 33466303, 2021). "POSTN was shown to induce proliferation in lung and gastric cancer cell lines." (PMID 33488671, 2020). "Similarly, another study used immunohistochemistry and immunofluorescence to show that POSTN was localized to stromal fibroblasts in human samples of advanced gastric cancer." (PMID 26086719, 2015). "The application of scRNA-seq in human gastric cancer (GC) has identified a prior undetected subset of CAF, characterized by high expression of Periostin (POSTN), which encodes a protein that functions as an adhesion-modulating factor in the ECM component." (PMID 37784082, 2023).
gastric cancer (continued). "In another previous study, the results have demonstrated the over-expression of POSTN in cancer-associated fibroblasts (CAFs) and suggested that POSTN constitutes the primary tumour niche by supporting cancer cell proliferation through the ERK signalling pathway in gastric cancer." (PMID 35865633, 2022). "In gastric cancer (GC), researchers identified a subtype of ECM CAFs (eCAFs), characterized by high expression of Periostin (POSTN), a protein involved in ECM remodeling and cell adhesion." (PMID 41164803, 2025). "The study highlights that FAK/YAP signaling promotes IL-6 expression in gastric cancer cells, and IL-6 acts as a positive feedback loop to activate the PI3K/AKT pathway further to produce more periostin." (PMID 38562556, 2024). "For instance, it was demonstrated that PDPN-positive CAFs secreted periostin, which activates FAK/YAP signaling in gastric cancer cells, resulting in activation of the PI3K/AKT pathway, which positively regulates periostin." (PMID 40741180, 2024). "Further, POSTN signaling via the AKT and YAP pathways increases metastasis of gastric cancer." (PMID 38275881, 2024). "Besides, high expression of five genes, POSTN, COL5A2, COL1A1, FN1, and MMP2, was revealed by Kaplan–Meier survival curve analysis to suggest a poor prognosis for gastric cancer patients." (PMID 37461041, 2023). "Periostin also increases cancer cell proliferation and EMT in nicotine-induced gastric cancer." (PMID 28754000, 2017).
atopic dermatitis (34 papers, 2015 to 2025). "It was reported that periostin, osteoblast specific factor, a protein encoded by the POSTN gene exacerbates the pathogenesis of atopic dermatitis in mice." (PMID 25585689, 2015). "In support of this, deficiency of POSTN or inhibition of α5 integrin (ITGA5) prevented development or progression of skin inflammation in an atopic dermatitis mouse model." (PMID 25678896, 2015). "Lastly, periostin has recently been suggested to be a marker to discriminate atopic dermatitis from psoriasis since it is known to be very highly expressed in atopic dermatitis, where it positively correlates with disease activity." (PMID 39201477, 2024). "Periostin plays a vital role in tissue repair; however, excessive or prolonged periostin expression can intensify the development of tumors, bronchial asthma, atopic dermatitis, polycystic kidney disease, and other fibrotic conditions." (PMID 38711706, 2024). "In contrast to atopic dermatitis, psoriatic basal keratinocytes are in an activated state and show a stable wound healing-like phenotype with the overexpression of periostin." (PMID 37773198, 2023). "Fibroblast-derived dermal periostin has well-known functions in wound healing and Th2-mediated diseases, such as atopic dermatitis." (PMID 37773198, 2023). "Periostin has been shown to play a role in Th2 pathway-mediated inflammatory diseases, such as atopic dermatitis, where interleukin-4 and interleukin-13 cytokines have been reported to activate periostin production in fibroblasts." (PMID 37773198, 2023). "Previously, several studies have explained the roles of periostin in inflammatory skin diseases, particularly, atopic dermatitis (AD) and scleroderma." (PMID 36598904, 2023). "We also found significantly elevated serum periostin in psoriatic patients compared to healthy individuals, but in contrast to patients with atopic dermatitis, interestingly, its level was the highest in systemically treated patients." (PMID 37773198, 2023). "The role of periostin in wound healing and other inflammatory skin diseases, such as atopic dermatitis, is relatively well-known." (PMID 37773198, 2023). "The role of periostin has been widely investigated in atopic dermatitis, a skin disease with very different immunopathology compared to psoriasis." (PMID 37773198, 2023). "Periostin was shown to be elevated not only in the inflamed dermis but also in the serum of atopic dermatitis patients and its level correlated with disease severity suggesting that periostin is an accelerator of atopic dermatitis progress." (PMID 37773198, 2023). "Increased serum periostin is detected in patients with atopic dermatitis and psoriasis, but its level is the highest in atopic dermatitis and correlates with disease severity." (PMID 37773198, 2023). "In contrast to lesional skin of atopic dermatitis, where Th2-type cytokines stimulate fibroblasts to increase periostin production, in psoriatic skin basal keratinocytes play a key role in enhanced periostin production." (PMID 37773198, 2023). "Fucoidan significantly altered gene expression in the atopic dermatitis model, and there was a trend to reduce periostin levels." (PMID 33806193, 2021). "A variety of different allergic diseases, among them bronchial asthma and atopic dermatitis (AD), have been shown to be connected to periostin expression." (PMID 34512647, 2021). "Together with beneficial gene regulation, subtle inhibition of periostin release and remarkable inhibition of S. aureus adhesion, fucoidan offers a promising therapeutic potential against skin inflammatory disease such as atopic dermatitis and related damages." (PMID 33806193, 2021). "Periostin is highly expressed in inflammatory skin conditions such as atopic dermatitis and increases proliferation and differentiation of keratinocytes." (PMID 34571811, 2021).
atopic dermatitis (continued). "It was observed that periostin enhances the pathogenesis of atopic dermatitis (AD) through TSLP production from keratinocytes in an AD mouse model and in vitro co-culture system of keratinocytes." (PMID 33203095, 2020). "Results from a previous study demonstrated that periostin directly induces IL-25, a key cytokine in the initiation of the inflammatory cascade in atopic dermatitis via NF-κB activation in keratinocytes." (PMID 26890265, 2016). "For patients with atopic dermatitis (AD), serum levels of periostin were significantly higher than in patients with psoriasis vulgaris (PV) and healthy controls." (PMID 25981515, 2015). "Studies have reported elevated levels of inflammatory cytokines, such as IL-4 and IL-13 and periostin, in the tear fluid of atopic dermatitis patients, which may exacerbate allergic responses on the ocular surface." (PMID 40718327, 2025). "Notably, PIEZO2hi fibroblasts highly expressed IL33 and POSTN, genes involved in the pathogenesis of itch in atopic dermatitis, while they showed a relatively lower expression of genes associated with chemical itch than did PIEZO2lo fibroblasts." (PMID 40742741, 2025). "Notably, signaling pathways such as NOTCH and PERIOSTIN, crucial for the renewal of differentiation homeostasis in skin cells, exhibited reduced expression of NOTCH receptors associated with atopic dermatitis." (PMID 38289616, 2024). "As symptoms of atopic dermatitis improve, serum periostin level decreases to normal level." (PMID 37773198, 2023). "However, growing evidence suggests that overexpression of periostin is involved in the pathogenesis of many inflammatory skin diseases, including atopic dermatitis (AD), psoriatic lesion, and scleroderma." (PMID 36598904, 2023). "In this research, we sought to understand how fucoidan might affect gene expression and periostin production in an in vitro 3D-RHE of keratinocyte model of atopic dermatitis using Th2-mediated cytokines." (PMID 33806193, 2021). "Periostin has also been shown to promote inflammation in experimental models of allergic disease, including models of HDM-induced atopic dermatitis, ovalbumin (OVA)-induced allergic rhinitis, and A. fumigatus-induced eosinophilices ophagitis." (PMID 25981515, 2015). "While a number of other conditions such as atopic dermatitis, rhinosinusitis, and malignancies may contribute to elevated periostin levels we did not utilize these as exclusion criteria." (PMID 30065761, 2018).